CRYBB2 (crystallin beta B2)
Diseases named in the same sentence as CRYBB2 in open-access papers (continued):
Sharing a sentence is not in itself a finding about the gene and the disease.
tumor (10 papers, 2009 to 2025). "Nevertheless, the documented association between CRYBB2 expression and multiple tumor types suggests that CRYBB2/CRYBB2P1 may serve as promising diagnostic or prognostic biomarkers in specific populations." (PMID 34118792, 2021). "Additionally, overexpression of CRYBB2 which is associated with the WNT signaling pathway involved in tumor progression, growth, differentiation and metastases may also contribute to worse survival observed in black patients with RCC." (PMID 28029648, 2017). "Among these, the expression of phosphoserine phosphatase like (PSPHL) and Beta-crystallin B2 (CRYBB2) were significantly elevated in the tumor stroma of AA men compared to EA patients." (PMID 34071280, 2021). "Still, for other tumor types and other populations, e.g., Asians, the correlation between CRYBB2/CRYBB2P1 expression and cancer progression and prognosis remains less certain." (PMID 34118792, 2021). "Although molecular evidence is still inconclusive, these findings suggested that differential expression of CRYBB2/CRYBB2P1 contribute to poor outcomes in African American women by impacting tumor cell proliferation, invasion, metastasis, and tumor immunity." (PMID 34118792, 2021). "Distinct tumor biology was identified with differential expression of 283 genes and enrichment of the VEGF pathway, immune system pathways and overexpression of CRYBB2 associated with the WNT pathway in black patients." (PMID 28029648, 2017). "Recent research in tumor research indicates that CRYBB2 is involved in carcinogenesis." (PMID 39318470, 2024). "Interestingly, the overexpression of the CRYBB2 gene in triple negative breast cancer cells promoted tumor progression by increasing growth, invasiveness, IL6 production, immune cell chemo attraction, and the expression of metastasis-associated genes." (PMID 34071280, 2021). "Nonetheless, we find a subset of genes such as CRYBB2, RPS26, XRRA1, FAM118A,andC2ORF74, all of which show predictive gains of >50% from SNPs in multiple cancers and tumour-adjacent tissue." (PMID 40041206, 2025). "The differential expression of CRYBB2 and the pseudogene CRYBB2P1 contributes to poor outcomes of breast cancer in African American women by affecting tumor cell proliferation, invasion, metastasis, and tumor immunity." (PMID 39318470, 2024). "For two of these genes, CRYBB2 and PSPH, expression levels were not only different in tumor epithelium but benign stroma as well." (PMID 36833598, 2023). "Follow-up studies from CBCS found associations between higher expression of PSPH and risk of recurrence (HR 1.76, 95% CI 1.15–2.68) and that both CRYBB2 and CRYBB2P1 promote tumor progression in vivo." (PMID 36833598, 2023). "Considering that no documented or hypothesized role for CRYBB2 in carcinogenesis has been explicitly put forward, it is conceivable that no causal relationship exists, at least for some malignancies, between high tumor CRYBB2 levels and tumor development." (PMID 34118792, 2021). "Examples of those included PSPHL, TMPO, CRYBB2, and AMFR in the tumor epithelium and PSPHL, CXCL10 and CXCL11 in the tumor stroma." (PMID 19225562, 2009). "Moreover, the increased expression of CRYBB2 in TNBC cell lines enhanced cell proliferation, tumor growth, interleukin 6 (IL6) production and expression of a panel of genes associated with EMT and metastasis." (PMID 34071280, 2021).
cancer (6 papers, 2013 to 2025). A tumor composed of atypical neoplastic, often pleomorphic cells that invade other tissues. "A higher expression of PSPHL and CRYBB2 in AA patients is also associated with cancer disparity in other malignancies including breast, colorectal, and endometrial, cancers." (PMID 34071280, 2021). "However, this required refined alignment of CRYBB2P1 reads due to potential cross-mapping with the ancestral CRYBB2 gene, which has also been attributed ethnic-specific disparity regarding cancer risk." (PMID 39199324, 2024). "Altogether, these findings reaffirmed the notion that CRYBB2 expression in cancer is impacted by ethnicity." (PMID 34118792, 2021). "We suggest further studies into the role, if any, which CRYBB2 plays in cancer and health disparity." (PMID 24324792, 2013). "Notably, overexpression of either CRYBB2, the gene encoding for βB2-crystallin in humans, or its highly homologous pseudogene, CRYBB2P1, correlates with differential survival outcomes in African American patients with different malignant tumors." (PMID 34118792, 2021).
genetic diseases (1 paper, 2023). "Thus, our study enlarges the CRYBB2 mutation spectrum and associated phenotypes to help clinical diagnosis of human genetic diseases." (PMID 37680813, 2023).
CRYBB2 also shares sentences with these, for which no sentence is quoted: Microcornea (2 papers); 22q11.2 deletion syndrome (1); age-related macular degeneration (1); autism (1); autosomal dominant cataract (1); glioblastoma (1); muscle disorders (1); ovarian carcinoma (1); pancreatic cancer (1); post-inflammatory pulmonary fibrosis (1); prostate tumors (1); retinal degeneration (1); vitelliform macular dystrophy (1).